MAP4K4 (mitogen-activated protein kinase kinase kinase kinase 4)
Diseases named in the same sentence as MAP4K4 in open-access papers (continued):
Sharing a sentence is not in itself a finding about the gene and the disease.
lung adenocarcinoma (16 papers, 2013 to 2025). A carcinoma that arises from the lung and is characterized by the presence of malignant glandular epithelial cells. "Results from one previous study showed that MAP4K4 protein level was elevated in lung adenocarcinoma and its elevation was negatively associated with patients’ prognosis." (PMID 28306189, 2017). "The results showed that MAP4K4 was drastically elevated in lung adenocarcinoma independently of KRAS or EGFR mutation status." (PMID 28306189, 2017). "Identification of downstream signaling mediators of MAP4K4 is crucial for understanding the mechanisms underlying MAP4K4 regulation of lung adenocarcinoma cells." (PMID 28306189, 2017). "Results from wound healing assay and cell invasion assay further showed that MAP4K4 deficiency jeopardized the abilities of lung adenocarcinoma cells to migrate and to invade." (PMID 28306189, 2017). "Elevated MAP4K4 levels were observed in lung adenocarcinoma tissues compared with normal ones, with the MAP4K4 expression being also linked to poor patient prognosis as indicated by PFS and OS." (PMID 39990663, 2025). "Significant role of MAP4K4 in cancer progression has been reported seen in cervical cancer, pancreatic tumorigenesis and lung adenocarcinoma maintenance." (PMID 36922678, 2023). "MAP4K4 is one of the genes involved in the apoptosis signaling pathway, and its over-expression is a prognostic factor for lung adenocarcinoma." (PMID 33183223, 2020). "A study showed knockdown of MAP4K4 inhibited progression of lung adenocarcinoma in vivo and in vitro." (PMID 30429233, 2018). "The current study has identified MAP4K4 as a novel activator of MAPK/ERK signaling in lung adenocarcinoma." (PMID 28306189, 2017). "Our results further showed that downregulation of MAP4K4 prevented ERK reactivation in EGFR inhibitor erlotinib‐treated lung adenocarcinoma cells." (PMID 28306189, 2017). "This study has identified serine/threonine kinase mitogen‐activated protein 4 kinase 4 (MAP4K4) as a novel positive regulator of MAPK/ERK signaling in lung adenocarcinoma." (PMID 28306189, 2017). "Together, these results identified MAP4K4 as a novel activator of MAPK/ERK pathway in lung adenocarcinoma cells." (PMID 28306189, 2017). "Consistent with this, we have identified MAP4K4 as an import protein required for lung adenocarcinoma maintenance." (PMID 28306189, 2017). "MAP4K4 expression is closely associated with NSCLC progression and has an independent prognostic value in lung adenocarcinoma." (PMID 27935865, 2017). "The results from functional in vitro and in vivo studies showed that MAP4K4 was required for the maintenance of the malignant phenotype of lung adenocarcinoma." (PMID 28306189, 2017). "Knockdown of MAP4K4 inhibited proliferation, anchorage‐independent growth and migration of lung adenocarcinoma cells, and also inhibited human lung adenocarcinoma xenograft growth and metastasis." (PMID 28306189, 2017). "We performed IHC analysis of MAP4K4 on human lung adenocarcinoma TMAs containing 44 cases of cancer tissues on a slide." (PMID 28306189, 2017). "The TMA slides, obtained from the University of Pittsburgh Lung Specialized Program of Research Excellence (SPORE) and constructed using randomly selected archival lung adenocarcinomas with known EGFR and KRAS mutation status, were stained for MAP4K4." (PMID 28306189, 2017). "We further conducted in vivo experiments to validate the functional importance of MAP4K4 in lung adenocarcinoma cells." (PMID 28306189, 2017). "Downregulation of MAP4K4 also substantially inhibited anchorage‐independent growth of lung adenocarcinoma cells." (PMID 28306189, 2017). "Next, we examined the effect of MAP4K4‐specific small‐molecule inhibitor, PF‐06260933, on lung adenocarcinoma cell functions." (PMID 28306189, 2017). "Together, these findings provided first evidence that MAP4K4 regulates lung adenocarcinoma cell functions in vivo, presumably through inducing ERK activation." (PMID 28306189, 2017).
lung adenocarcinoma (continued). "Together, our findings identify MAP4K4 as a novel MAPK/ERK pathway regulator in lung adenocarcinoma that is required for lung adenocarcinoma maintenance." (PMID 28306189, 2017). "Furthermore, In EGFR-mutated and erlotinib-treated lung adenocarcinoma cell lines, downregulation of MAP4K4 prevented ERK reactivation, suggesting that MAP4K4 is critical for maintaining tumor growth." (PMID 37223681, 2023). "Targeting MAP4K4 could be a promising alternative mean of ERK pathway inhibition and MAP4K4 coinhibition could prevent or circumvent resistance to vertical inhibition of EGFR/RAS/RAF/MEK pathway in a broad range of patients with lung adenocarcinoma." (PMID 28306189, 2017). "But except for the correlative observations, whether and how MAP4K4 contributes to lung adenocarcinoma remain to be determined." (PMID 28306189, 2017). "Our findings suggest that pharmacological inhibition of MAP4K4 could be an effective approach to targeting lung adenocarcinoma, as a stand‐alone therapy or in combination with other treatment." (PMID 28306189, 2017). "Whether these kinases function as MAP4K4 downstream effector in lung adenocarcinoma remains to be determined." (PMID 28306189, 2017). "Our novel findings that PF‐06260933 significantly suppressed lung cancer cell functions and had synergistic inhibitory effect with MEK inhibitor on lung cancer cell proliferation suggest that MAP4K4‐specific inhibition could be a promising approach to treating lung adenocarcinoma." (PMID 28306189, 2017). "To determine whether MAP4K4 is functionally involved in lung adenocarcinoma cells, we performed a variety of in vitro assays to evaluate the impact of shRNA knockdown of MAP4K4 on cell functions including proliferation, anchorage‐independent growth, migration, and invasion." (PMID 28306189, 2017). "Moreover, negative correlation between MAP4K4 expression and patient prognosis has been reported in multiple types of human cancer, such as CRC, lung adenocarcinoma and HCC." (PMID 29970191, 2018).
colorectal cancer (14 papers, 2013 to 2025). A primary or metastatic malignant neoplasm that affects the colon or rectum. "Retention of exon 19 in MAP4K4 is associated with invasiveness in colorectal cancer, and MAP4K4 is essential for GBM invasion." (PMID 33499924, 2021). "A recent study reported that miR-194 was decreased and associated with tumor size and tumor differentiation in colorectal cancer, overexpression of miR-194 suppresses tumor growth by regulating the MAP4K4/c-Jun/MDM2 signaling pathway." (PMID 26909612, 2016). "In colorectal cancer, MAP4K4 inhibition via miR-141 increased tumor cell chemosensitivity and diminished their proliferation, invasion, and migration." (PMID 37223681, 2023). "The ability of MAP4K4 to phosphorylate JNK was also demonstrated in an in vitro model of colorectal cancer." (PMID 37223681, 2023). "MiR-194, commonly repressed in colorectal cancer, suppresses tumor growth by regulating the MAP4K4/c-Jun/MDM2 signaling pathway." (PMID 26909612, 2016). "Another study had similar findings regarding the role of miR-194 in colorectal carcinoma, though it suggested that miR-194 regulated the MAP4K4/c-Jun/MDM2 signaling pathway." (PMID 26909612, 2016). "MAP4K4 is similarly incorporated in numerous independent gene expression signatures which are predictive of survival in colorectal cancer and recurrence in prostate cancer." (PMID 24708576, 2014). "Notably, distinct isoforms of MAP4K4 were found to constitute a biological mechanism of MAP4K4 control in colorectal cancer, whereby isoforms 2 (NM_145686) and 5 (NM_001242560) of MAP4K4 contribute to a more aggressive phenotype." (PMID 36568222, 2022). "MAP4K4 was identified as a promigratory kinase in a genome wide siRNA screen for modulators of tumor cell motility and is part of a five-gene signature that is a positive predictor of metastasis and negative survival in colorectal cancer." (PMID 24163766, 2013).
Insulin resistance (14 papers, 2008 to 2025). Increased resistance towards insulin, that is, diminished effectiveness of insulin in reducing blood glucose levels. "MAP4K4 has also been implicated in a large number of biological processes including insulin resistance, focal adhesion disassembly, as well as cellular invasion and migration." (PMID 31913126, 2020). "In conclusion, common variation in MAP4K4 is associated with insulin resistance and β-cell dysfunction, possibly via this gene’s role in inflammatory signalling." (PMID 23094072, 2012). "We demonstrate an increase in TNF-α release causing upregulation of Map4k4 expression that disrupts the normal metabolic function of adipose tissue and thereby leads to insulin resistance." (PMID 22816003, 2012). "We investigated whether common single nucleotide polymorphisms (SNPs) in the MAP4K4 locus associate with glucose intolerance, insulin resistance, impaired insulin release, or elevated plasma cytokines." (PMID 23094072, 2012). "Our observations are consistent with these findings and indicate that the decreased insulin sensitivity observed following FTox-G50 injection is mediated by an increase in the TNF-α concentration in adipose tissue, which selectively stimulates the expression of Map4k4 to cause insulin resistance." (PMID 22816003, 2012). "T cell specific Map4k4 KO in mice leads to the development of hepatic steatosis, and insulin resistance." (PMID 36568222, 2022). "MAP4K4 is less well characterized than other members of the MAPK family but has been implicated in a number of biological processes including invasion, insulin resistance, and immunity." (PMID 31913126, 2020). "MAP4K4 downregulation in T cells results in enhancement of the IL-6+ Th17 cell population, leading to insulin resistance and T2D in both human and mice." (PMID 28061846, 2017). "MAP4K4 deficiency has been reported to stabilize TRAF2 and induce TRAF2/IL-6 upregulation, leading to insulin resistance." (PMID 28101327, 2017). "Another study has shown that insulin resistance can be abolished by Map4k4 silencing in skeletal muscle." (PMID 22816003, 2012). "We found that following venom injection, TNF-α increases Map4k4 expression in adipose tissue, promoting insulin resistance." (PMID 22816003, 2012). "Map4k4 gene silencing in human skeletal muscle prevents tumor necrosis factor-alpha-induced insulin resistance." (PMID 18570670, 2008). "MAP4K4 expression is induced by TNF-alpha and promotes insulin resistance, whereas silencing of MAP4K4 prevents insulin resistance in human skeletal muscle and enhances glucose uptake." (PMID 18671879, 2008). "MAP4K4 downregulates IL-6 production in T cells through direct phosphorylation and degradation of TNF receptor-associated factor 2 (TRAF2), leading to the suppression of Th17 cell-mediated insulin resistance in vivo." (PMID 36568222, 2022). "Thus, MAP4K4 is involved in inflammatory signalling and is a potential mediator of cytokine-induced cellular insulin resistance." (PMID 23094072, 2012). "Over-expressed MKK6/3-p38/MAPK in L6 myotubes was reported to deteriorate the action of GLUT4 via down-regulation of GLUT4 gene expression, whereas knock-down MAP4K4, the upstream kinase of ERK1/2 and JNK, inhibits TNF-α-induced insulin resistance." (PMID 29955954, 2019). "TNF-α stimulates the expression of key components of its own signaling pathway, notably Map4k4, through a TNFR1-dependent mechanism to induce insulin resistance in adipose tissue." (PMID 22816003, 2012). "Our findings for the effects of the TNF-α inhibitor etanercept and for Map4k4 expression strongly suggest that the venom-induced insulin resistance is TNF-α-dependent and was mediated at least in part by Map4k4 activation in adipose tissue." (PMID 22816003, 2012).
Insulin resistance (continued). "TNF-α selectively stimulates the expression of a key component of its own signaling pathway, Mitogen-activated protein 4 kinase isoform 4 (Map4k4), through a TNFR1-dependent mechanism to induce insulin resistance in adipose tissue." (PMID 22816003, 2012). "Mitogen-activated protein kinase kinase kinase kinase 4 (MAP4K4) is expressed in all diabetes-relevant tissues and mediates cytokine-induced insulin resistance." (PMID 23094072, 2012). "FTox-G50-induced insulin resistance in skeletal muscle was not abolished by anti-TNF-α treatment and Map4k4 expression was not activated in skeletal muscle of mice injected with FTox-G50." (PMID 22816003, 2012).
glioblastoma (11 papers, 2013 to 2025). The most malignant astrocytic tumor (WHO grade IV). "Another study employed large-scale CRISPR-Cas9 loss of function screen and identified MAP4K4 as a strong regulator of glioblastoma invasion." (PMID 36922678, 2023). "Furthermore, we found that loss of MAP4K4 function drives glioblastoma cells into a non-invasive state." (PMID 31570734, 2019). "In an in vitro model of glioblastoma multiforme, MAP4K4 inhibition reduced the invasion of tumor cells." (PMID 37223681, 2023). "Further up-regulation of MAP4K4 compared to corresponding normal tissue controls has been noted in the aggressive primary brain tumors glioblastoma and medulloblastoma." (PMID 36568222, 2022). "In summary, we used CRISPR-Cas9 to screen for genes essential for human glioblastoma invasion and found that MAP4K4 plays an important role in brain tumor invasion." (PMID 31570734, 2019). "Our results identify MAP4K4 as a critical protein required for cell invasion and validate the necessity of MAP4K4 in four separate human glioblastoma cell lines, while also highlighting the utility of a specific drug inhibitor of MAP4K4." (PMID 31570734, 2019). "Future studies will be necessary to examine the EGFR/MAP4K4/Arp2 pathway in glioblastoma invasion further." (PMID 31570734, 2019). "In summary, we used a large-scale pooled library CRISPR-Cas9 approach to screen for genes necessary for glioblastoma invasion and discovered MAP4K4 as a promising therapeutic target." (PMID 31570734, 2019). "We found MAP4K4 expression correlates with epithelial-mesenchymal transition in glioblastoma and that eliminating MAP4K4 reverses this transition." (PMID 31570734, 2019). "Finally, experiments with CRISPR-Cas9 in an in vitro model of glioblastoma multiforme demonstrated that MAP4K4 was involved in cell motility and tumor invasion." (PMID 37223681, 2023). "Alternative splicing and exon retention in MAP4K4 was also associated with recurrent but not primary glioblastoma." (PMID 36568222, 2022). "Our results identify MAP4K4 as a novel potential therapeutic target to limit glioblastoma invasion." (PMID 31570734, 2019). "To establish the importance of MAP4K4 function in cell motility for glioblastoma beyond the U138 human glioma line used for this screen, we used a specific drug inhibitor to demonstrate reduced migration in a wound healing assay in three additional adult malignant glioma lines." (PMID 31570734, 2019). "We found MAP4K4 influences EMT markers in glioblastoma cells." (PMID 31570734, 2019). "Therefore, the current results suggest that inhibition of the interaction of MAP4K4 and Pyk2 may represent a potential therapeutic strategy to limit glioblastoma tumor dispersion." (PMID 24163766, 2013). "In glioblastoma (GBM), lactylation of histone H3 increases the expression of LINC01127, which directs polymerase II (POLR2A) to the mitogen-activated protein kinase kinase kinase kinase 4 (MAP4K4) promoter region." (PMID 40584966, 2025). "It has been reported that miR-141-3p would promote the EMT process by targeting MAP4K4, and MAP4K4 could promote EMT reprogramming in glioblastomas." (PMID 36292671, 2022).
type 2 diabetes (10 papers, 2012 to 2023). "Alterations in MAP4K4 function have a central role in the development of many metabolic diseases such as atherosclerosis and type 2 diabetes, but have recently been implicated in the initiation and progression of cancer." (PMID 37223681, 2023). "Interestingly, common polymorphisms of the MAP4K4 locus are associated with type 2 diabetes and insulin resistance." (PMID 30679431, 2019). "Besides its essential role in embryonic development, MAP4K4 has also been implicated in focal adhesion dynamics regulation, systemic inflammation, lung inflammation, type 2 diabetes, atherosclerosis and insulin sensitivity." (PMID 27800153, 2016). "Furthermore, MAP4K4 has critical roles in the regulation of cell adhesion and inflammation, and has been implicated in the development of metabolic diseases such as type 2 diabetes and atherosclerosis." (PMID 37223681, 2023). "MAP4K4 have been involved in focal adhesion dynamics regulation, systemic inflammation, lung inflammation, type 2 diabetes, atherosclerosis, insulin sensitivity, and cancer." (PMID 33668405, 2021). "From this information, it can be considered for the analysis if hsa-miR-933 can regulate the overexpressed PEA15, downregulated BDNF, or other ATF2 target genes (PRKACB, GNAS, PRKCE, and MAP4K4) to control type II diabetes mellitus." (PMID 32993798, 2020). "Since 2-hour glucose is commonly used to classify impaired glucose tolerance and type 2 diabetes, common genetic variation within MAP4K4 affects a (pre)diabetes-relevant trait." (PMID 23094072, 2012). "MAP4K4 has been enriched in several GO terms including MAP kinase c kinase activity (GO:0008349), which is an important contributor to the risk of developing type 2 diabetes mellitus in a Chinese Han population." (PMID 32117227, 2020). "This raises the question why MAP4K4 SNPs were not among the top signals for type 2 diabetes detected by array-based genome-wide association (GWA) studies and consortia-driven meta-analyses thereof." (PMID 23094072, 2012). "The target genes that were significantly enriched for the development of type II diabetes mellitus in both modules are GNAS, PRKACB, PRKCE, MAP4K4, PEA15, and BDNF." (PMID 32993798, 2020). "In this context, it can be considered if hsa-miR-933 can also regulate MAP4K4 or other protein kinases (PRKCE, PRKACB) to control type II diabetes mellitus." (PMID 32993798, 2020). "A recent study points to a possibility that in T cells of type 2 diabetes patients, mRNA level of MAP4K4 might be affected by enhanced methylation of CpG islands in its promoter region, suggesting epigenetic regulation could play a role in the regulation of MAP4K4 expression." (PMID 27800153, 2016). "Our approach delineated that hsa-miR-933 might control the hyperglycemic condition and hyperinsulinism by regulating ATF2 target genes MAP4K4, PRKCE, PEA15, BDNF, PRKACB, and GNAS which can otherwise lead to the development of type II diabetes mellitus." (PMID 32993798, 2020).